TIMP1 (TIMP metallopeptidase inhibitor 1)
Diseases named in the same sentence as TIMP1 in open-access papers (continued):
Sharing a sentence is not in itself a finding about the gene and the disease.
heart failure (45 papers, 2012 to 2026). Inability of the heart to pump blood at an adequate rate to meet tissue metabolic requirements. "Episodes of ventricular tachyarrhythmia, potentially involved in sudden cardiac death, were associated with higher MMP‐9 levels, and particularly MMP-9/TIMP‐1 ratios in heart failure patients." (PMID 31932967, 2021). "Previous studies conducted on rats have shown that the plasma levels of MMP-2 and TIMP-1 reflect heart failure associated with haemodynamic, functional, and morphological changes." (PMID 34930125, 2021). "Comparable findings have been reported in the LAD ligation model 14-days post-MI57, implying the increased MMP activity provided from TIMP-1 deficiency promotes adverse myocardial remodelling, accelerating subsequent heart failure." (PMID 34848763, 2021). "Heart histological staining and mRNA levels of genes associated with heart failure (Acta1 and Nppa), inflammation (IL‐6), and fibrosis (Ctgf, Col1a2, Timp1, and Mmp9) were assessed." (PMID 32133617, 2020). "Positive associations between TIMP-1 and mortality were encountered in the general population, patients who underwent coronary angiography and in patients with heart failure." (PMID 28446168, 2017). "In hypertensive patients with heart failure but normal ejection fraction, elevated estimated capillary wedge pressure compared with normal LV filling pressure was associated with higher TIMP-1 levels and a lower metalloproteinase-1 to TIMP-1 ratio, indicative of lower breakdown of collagen." (PMID 27959898, 2016). "This study represents the first report identifying TIMP1 as a hub gene orchestrating the glycolysis-ketone metabolism-immune imbalance axis in heart failure." (PMID 41393260, 2025). "This study is the first to establish TIMP1 as the central hub integrating dysregulation of the glycolysis-ketone metabolism axis with immune microenvironment imbalance in heart failure." (PMID 41393260, 2025). "Studies demonstrate that TIMP1 mRNA and protein are significantly upregulated in deteriorating heart failure patients and in cardiac tissue from patients with chronic pressure overload." (PMID 41393260, 2025). "This interpretation is further supported by recent findings showing that TIMP1 gene transcriptional activity decreases with advancement of heart failure, particularly in ischemic cardiomyopathy with severe dysfunction." (PMID 41393260, 2025). "This study identifies TIMP1 as a central regulator linking glycolysis-ketone metabolic imbalance with immune microenvironment dysregulation in heart failure." (PMID 41393260, 2025). "While this study elucidates the TIMP1-mediated metabolic-immune regulatory network in heart failure, several limitations warrant acknowledgment." (PMID 41393260, 2025). "The levels of ANP, BNP, NT-ProBNP, PICP, MMP-2, MMP-9, and TIMP-1 in rat serum reflect the severity of heart failure, and the level of cAMP in myocardial tissues can reflect the activity of the cAMP signaling pathway." (PMID 38402401, 2024). "TIMP-1 is induced in heart failure, and TIMP-4 is highly expressed in the heart and is decreased during chronic cardiac failure." (PMID 39727952, 2024). "The biomarkers MMP-2, TIMP-1, GDF-15, and OPN were particularly notable for their strong associations with adverse clinical outcomes, including heart failure events and all-cause mortality." (PMID 39334904, 2024). "Higher circulating MMP‐9 and TIMP‐1 levels and MMP-9/TIMP‐1 ratios were reported in ischemic cardiomyopathy and are associated with disease severity in heart failure and tissue remodeling in myocardial hypertrophy." (PMID 31932967, 2021). "In the DOCA-salt hypertensive rat model spironolactone treatment caused improvement in functional parameters of heart failure and lower plasma MMP-2 and TIMP-1 concentrations." (PMID 31141909, 2019).
heart failure (continued). "Results of different clinical trials suggest that plasma MMP-2 and TIMP-1 concentrations can be useful to assess disease severity in patients suffering from hypertrophic cardiomyopathy or heart failure." (PMID 31141909, 2019). "Circulating levels of MMP-2 and TIMP-1 are also elevated in chronic HF patients, significantly correlated with HF development, and correlated with the severity of heart failure." (PMID 31141909, 2019). "Mice with TIMP-1 genetic defects have obvious signs of ventricular remodeling and cardiac insufficiency after myocardial damage." (PMID 25861361, 2015). "Our study showed significant overexpression of Timp1, -2 and -3, similar to the end-stage human heart failure." (PMID 24206753, 2013). "The suggested TIMP-1 could modulate ventricular remodeling and subsequent heart failure to impact the long-term patency of CABG." (PMID 39195176, 2024). "During the initial 12 hours post-fibrinolysis, increased MMP-1 activity due to inadequate TIMP-1 inhibition may contribute to adverse outcomes, including more frequent heart failure symptoms observed in patients with a lysis-PCI interval of ≤9.6 hours." (PMID 39877021, 2024). "Moreover, TIMP-1 gene transcriptional activity correlated negatively with the advancement of heart failure (decrease in left ventricular ejection fraction)." (PMID 38540214, 2024). "For the determinants of aggravated heart failure, we performed another forward stepwise analysis and found that TIMP1 and NT-proBNP were the major determinants for the presence of aggravated heart failure (OR: 1.025, 95% CI: 1.001–1.050 and OR: 1.010, 95% CI: 1.003–1.017, respectively)." (PMID 30413105, 2018). "In particular, an increase of TIMP-1 appears associated with the raising of circulating levels of MMP-2 and MMP-9, not only in patients at the final stage of heart failure (or in the acute state of decompensation), but also in patients with subclinical heart failure." (PMID 26495844, 2015). "The aim of the study was to assess the occurrence of classic risk factors in the study group of patients with heart failure and to link them with the transcriptional activity of the examined genes: metalloproteinase 9 (MMP-9) and the tissue inhibitor of metalloproteinases 1 (TIMP-1)." (PMID 38540214, 2024). "Interestingly, suppression of TIMP1 in mice has been linked to maintenance and expansion of stem cells with no increased risk of cancer, while the serum level of IGFBP7 is a marker of tissue aging and heart failure." (PMID 33512769, 2021). "Furthermore, genes for fibrotic regulators, such as TGFβ1, TIMP1, TIMP3, TIMP4, and ADAMTS1, were linked to CLIC expression, reinforcing the hypothesis that CLICs contribute to fibrotic progression and ECM remodeling in human heart failure." (PMID 41521401, 2026). "Another study, which explored the potential significance of MMP and TIMP levels in the blood of adult patients with heart failure, found that MMP-9, along with MMP-2 and TIMP-1, serves as a mortality predictor." (PMID 39466144, 2025). "An upregulation of TIMP1 and downregulation of TIMP4 has been observed by others in the working myocardium in various species and heart failure models." (PMID 37122221, 2023). "Disparity between TIMP‐1 and MMP‐9 levels was also shown to contribute to adverse events and mortality in heart failure patients." (PMID 31932967, 2021). "The inhibitors of MMP‐2 and MMP‐9, TIMP‐1 and TIMP‐2 are elevated in tissue and plasma during heart failure and myocardial infarction." (PMID 31932967, 2021). "Wnt5a induces IL-6 and TIMP-1 by activation of ERK in CFs, resulting in cardiac inflammation and subsequent heart failure progression." (PMID 34564708, 2021). "Elevated MMP2, TIMP1, collagen type I and III levels were reported in patients with hypertrophy and heart failure." (PMID 27494843, 2016). "Together with changes of cardiac function, it has been shown that TIMP-1 interacts with MMP-2 and MMP-9 in patients with heart failure." (PMID 26495844, 2015).
heart failure (continued). "Among Tc+ individuals, those with cardiac insufficiency had higher levels of BNP, NTproBNP, troponin I, MMP-2, TIMP-1, and TIMP-2 than those with normal ejection fraction and left ventricular diameter." (PMID 25275382, 2014). "Considering TTC biopsy data and the previous findings in heart-failure patients, we suggest that the severity of TTC may be affected by fibrosis due to low MMP-8 and high TIMP-1 levels." (PMID 28278213, 2017). "In a systematic review and meta-analysis, only Timp1 levels were greater in hypertensive than normotensive patients, whereas both Timp1 and Mmp2 levels were greater in hypertensive patients with heart failure than hypertensive patients without heart failure." (PMID 28880918, 2017). "Moreover, TIMP-1 has been found to be a predictor of the new onset of CKD and heart failure, regardless of age, gender, and biomarkers of systemic inflammation (c-reactive protein and brain natriuretic peptide)." (PMID 31963569, 2020).
ovarian carcinoma (45 papers, 1998 to 2025). A malignant neoplasm originating from the surface ovarian epithelium. "It has been shown that elevated TIMP1 expression in plasma and tumors of patients with breast, colorectal, gastric and ovarian cancer, is associated with poor prognosis." (PMID 36158681, 2022). "On the one hand, multiple studies indicate an association between the level of TIMP-1 expression and poor prognosis in patients with ovarian cancer." (PMID 34572929, 2021). "It should be noted that TIMP-1 is a protein associated with the described role in the progression of ovarian cancer and associated with poor clinical outcomes." (PMID 34572929, 2021). "On the other side, TIMP1 deficient cells showed higher capacity to adhere to collagen, suggesting a role of this protein in the adhesive characteristics of ovarian cancer cells." (PMID 32423054, 2020). "Low serum TIMP-1 concentration at the end of first-line chemotherapy treatment in ovarian cancer was found to be associated with an improved survival rate of patients." (PMID 29393911, 2018). "In line with the present data, preoperative serum TIMP-1 concentration showed insufficient diagnostic power (AUC = 0.730) in differentiating between low malignant potential and malignant ovarian tumors." (PMID 28662671, 2017). "The primary aim of the present study was to evaluate TIMP-1 protein immunoreactivity in tissue from primary ovarian cancer patients and associate these findings with the course of the disease including response to treatment in the individual patient." (PMID 20459644, 2010). "One study including 40 patients with ovarian cancer found that increasing preoperative plasma levels of TIMP-1 were associated with poor survival." (PMID 20459644, 2010). "This is underlined by the findings in the present study where TIMP-1 immunoreactivity was significantly lower in patients with serous histology, which constitutes the major part of epithelial ovarian cancers." (PMID 20459644, 2010). "TIMP-1 is associated with chemotherapy resistance in ovarian cancer cells." (PMID 38172678, 2024). "The primary aim of the present study was therefore to evaluate whether TIMP-1 immunoreactivity in tissue from primary ovarian cancer patients was associated with overall survival of the patients." (PMID 20459644, 2010). "Overexpression of TIMP1 in ovarian cancer cell lines recapitulated CSC features, including treatment and anoikis resistance, stem cell marker expression, and enhanced migration." (PMID 40427104, 2025). "Overexpression of TIMP1 in ovarian cancer cell lines was able to recapitulate several features of the ovarian cancer stem cell phenotype, including treatment resistance, expression of stem cell markers, and anoikis resistance." (PMID 40427104, 2025). "In conclusion, this study highlights the role of CSC-secreted TIMP1 in ovarian cancer progression, therapy resistance, and metastasis." (PMID 40427104, 2025). "In ovarian cancer, the diagnostic usefulness was previously shown for plasma MMP7 and TIMP1 levels in a panel with Ca125 and He4." (PMID 38397798, 2024). "Some recent studies on established cancer cell lines belonging to NSCLC and ovarian cancer have also suggested a potential role for TIMP-1 in Cis-Pt resistance." (PMID 37443843, 2023). "We have also shown diverse expression of TIMP-1, TIMP-2 and associated MMPs in ascites and ovarian cancer cell lines, and changes in the expression of these proteins in response to chemotherapy treatments." (PMID 36585738, 2022). "During the formation of metastases of ovarian cancer, TIMP-1 can be most commonly detected in the omentum." (PMID 34572929, 2021). "Overexpression of MMP-9, together with the imbalance between MMP-9 and TIMP-1, play an important role in the development of ovarian cancer, when the blood serum level of TIMP-1 is elevated." (PMID 34572929, 2021).
ovarian carcinoma (continued). "In that context, molecular characterization of epithelial circulating cells in patients with disseminated ovarian cancer has shown significantly high expression of TIMP-1 suggesting the utility of TIMP-1 as a biomarker for disseminated disease." (PMID 35047406, 2021). "There is a scarcity of data regarding the concentrations of adiponectin and TIMP-1 in ascites in the course of ovarian cancer." (PMID 34572929, 2021). "It has also been shown that the expression of MMP-9 and TIMP-1 induced by the epidermal growth factor (EGF) in ovarian cancer cell lines results in increased migration and mass spread induced by EGF." (PMID 34572929, 2021). "Although the molecular mechanisms behind the role of TIMP1 for ovarian cancer proliferation and dissemination should be studied in more detail, our results open an interesting line of research, indicating its value as a potential therapeutic target." (PMID 32423054, 2020). "The mRNA expression of TIMP-1, − 2 and − 3 was measured in the ovarian cancer cell lines, JHOS2 and OVCAR4 and a Fallopian tube secretory epithelial cell line, FT282, which was used as a non-cancer control." (PMID 33023532, 2020). "A recent study has also evidenced the increment of TIMP1 expression in platinum-resistance ovarian cancer cells and its interest to predict global patients with advanced tumors." (PMID 32423054, 2020). "The high serum concentration of TIMP1 is related to poor prognosis in ovarian cancer and in many other malignant tumors." (PMID 32526853, 2020). "EGF induced MMP-9 and TIMP-1 expression in ovarian cancer cell lines has been shown to result in increased migration and robust EGF-induced invasion." (PMID 29393911, 2018). "About 15 studies have been published on the prognostic value of MMP-2, MMP-7, MMP-9, MT1-MMP, TIMP-1 or TIMP-2 in ovarian cancers, but the results remain controversial." (PMID 22200690, 2012). "Over-expression of TIMP-1 has also been reported in ovarian cancer patients compared to patients with borderline tumours, benign ovarian tumours or with normal ovaries." (PMID 20459644, 2010). "The aim of the current study was to evaluate the role of serum VEGF-165 and TIMP-1 to monitor therapy and predict clinical outcome in patients with ovarian cancer in comparison to established clinicopathological parameters and CA-125." (PMID 20388222, 2010). "A second study found that high preoperative serum concentrations of TIMP-1 from 59 ovarian cancer patients were correlated with decreased recurrence-free survival and overall survival in univariate analysis." (PMID 20459644, 2010). "TIMP-1 protein is present in the tumour tissue in a subgroup of patients with primary epithelial ovarian cancer." (PMID 20459644, 2010). "TIMP-1 was assessed by immunohistochemistry (in tissue micro arrays) in a total of 163 ovarian cancer specimens obtained from primary debulking surgery during 1991-1994 as part of a randomized clinical protocol." (PMID 20459644, 2010). "This study is the first comprehensive longitudinal analysis of serum VEGF-165 and TIMP-1 in patients with ovarian cancer." (PMID 20388222, 2010). "Cell line data indicated that TIMP1 was released from ovarian cancer cells at nanograms per million cancer cells per hour which would account for increased levels in human ovarian cancer patient samples." (PMID 19936259, 2009). "Increased protein levels for Timp1, Lcn2, Igfbp2, Pfn1, and Sparc were observed in ovarian tumor tissues isolated from K-ras/Pten and Pten/Apc ovarian cancer mouse models compared to control tissue lysates." (PMID 19936259, 2009). "The imbalance of MMPs and TIMP-1 might contribute to the enhanced motility and invasion observed in ovarian cancer cells with GPC3 knockdown." (PMID 40422229, 2025).